CRP (C-reactive protein)
Diseases named in the same sentence as CRP in open-access papers (continued):
Sharing a sentence is not in itself a finding about the gene and the disease.
leukocytosis (continued). "Most dogs underwent cardiac examination and did not undergo CRP measurements unless they exhibited leukocytosis." (PMID 37760221, 2023). "Labwork generally does not show specific changes, but the most commonly found are leukocytosis, neutrophilia, increased erythrocyte sedimentation rate, increased C-reactive protein (CRP), hyponatremia, and hypoalbuminemia." (PMID 37189542, 2023). "Although there was no leukocytosis or elevation of C-Reactive Protein, hematogenous bacterial pyelonephritis was suspected and cefotaxime was added." (PMID 40041280, 2023). "This patient had notable abnormalities of leukocytosis, thrombocytosis, and an elevated C-reactive protein, but these are all nonspecific elevations and did not hint toward a diagnosis." (PMID 36049202, 2022). "Pregnant women have a higher proportion of leukocytosis (27% vs. 14%) and thrombocytopenia (18% vs. 12%) and a lower proportion of raised C-reactive protein (52% vs. 81%) compared with nonpregnant patients." (PMID 36263236, 2022). "Notably, laboratory reports revealed C-reactive protein (CRP) at 340 mg/L, procalcitonin (PCT) at 65 μg/mL, and leukocytosis at 24 × 109/L, suggesting a severe condition." (PMID 35056629, 2022). "Paraclinically, both long-term COVID-19 syndrome and MIS are characterized by elevated C-reactive protein, ESR, fibrinogen, ferritin, procalcitonic, leukocytosis or lymphopenia, and increased NT-proBNP, while leukopenia with lymphopenia was the most common change reported in patients with MIS-C." (PMID 36016309, 2022). "Laboratory tests showed an increase in the C-reactive protein (CRP) up to 28.6 mg/L (reference < 5 mg/L), but no leukocytosis." (PMID 35974355, 2022). "Our study suggests that leukocytosis, neutrophilia, and elevation of CRP are no longer accurate predictors of bacteremia." (PMID 35778478, 2022). "The evaluation of the selected blood parameters in the cohort indicated that 56.5% had lymphocytopenia, 35.4% had an elevated CRP level, 32% had an elevated LDH level, 30% had an elevated ALT level, 24% had an elevated D-dimer level, 22% had leukocytosis, and 12.5% had an elevated AST level." (PMID 35414616, 2022). "Moreover, inflammatory markers, including CRP and ESR, were mainly elevated in idiopathic pericarditis (n=15; 88.23%) and (n=7; 23.3%), respectively, as well as leukocytosis observed in nine (30%), next to low hemoglobinemia (Hb) in 17 (56.7%)." (PMID 36039227, 2022). "Laboratory investigation on presentation revealed leukocytosis (WBC 21 K/microliter), markedly elevated inflammatory markers (C-reactive protein (CRP) (23 mg/dl), erythrocyte sedimentation rate (ESR) (79 mm/h), fibrinogen (840 mg/dl), von Willebrand factor 289% (normal 60-160%), and hypoalbuminemia." (PMID 35012585, 2022). "In univariate analysis, the risk factors linked to mortality at hospital admission were older age of more than 40 years; leukocytosis; lymphocytopenia; neutrophilia; thrombocytopenia; elevated AST, ALT, and APTT; and raised creatinine, CRP, and ferritin concentration." (PMID 35983383, 2022). "In general, the blood count and laboratory chemistry, if any, show nonspecific changes such as moderate leukocytosis or CRP elevation at the onset of the disease." (PMID 36010350, 2022). "The biochemical analysis from our cohorts showed the typical spectrum of hematological alterations, including leukocytosis with neutrophilia and lymphopenia, increased values of plasma ferritin, LDH, CRP, and abnormal platelet count and procalcitonin levels as evidenced in most patients elsewhere." (PMID 35358185, 2022). "Laboratory examinations showed leukocytosis, hypoalbuminemia (2.3 g/dL), and elevated C-reactive protein level (305.5 mg/L) with no azotemia." (PMID 35758376, 2022). "Initial blood tests revealed kidney and liver dysfunction, leukocytosis, neutrophilia, lymphopenia, thrombocytopenia, elevated CRP, ferritin, and D-dimer, with a negative SARS COV 2 rapid antigen test." (PMID 36096831, 2022).
leukocytosis (continued). "We observed a significant reduction in the post-procedural leukocytosis (8650.8 ± 1890.3/mm3), but we did not evaluate the post-procedural CRP levels due to a slower resolution of the inflammatory syndrome." (PMID 35630036, 2022). "Leukocytosis and neutrophilia were found to be significant among patients admitted to the ICU and/or who died, in addition to significantly higher D-dimer, ferritin, and highly sensitive CRP levels, with a p < 0.0001 for all patients." (PMID 34055842, 2021). "For other adhesion prevention devices commonly used in gynecologic surgery, increased CRP values without leukocytosis or fever have not been prominently reported." (PMID 34357446, 2021). "According to the results of a systematic review, increased C-reactive protein (CRP) levels (49%), lymphopenia (33%), leukocytosis (26%), elevated procalcitonin levels (23%), abnormal liver enzymes (15.4%), and thrombocytopenia (6.6%) were the most common laboratory findings." (PMID 34536988, 2021). "C-reactive protein (CRP) increased, while leukocytosis was low (3300 Leukocytes per mL)." (PMID 34068785, 2021). "Overall, patients did not have fever or leukocytosis at baseline; though, CRP levels and ESR were mostly elevated." (PMID 33531081, 2021). "However, if there is an increased WBC, C reactive protein (CRP), proportion of polymorphonuclear (PMN) cells, or granulocyte count, then AA is more likely; while leukocytosis is reported in 71.26%(n=124) of the cases in our study." (PMID 34223182, 2021). "However, CRP, fibrinogen, CK, and ALT and leukocytosis, were altered in 4, 3, 2, and 1 of them, respectively." (PMID 33841437, 2021). "Blood laboratory examinations indicated no leukopenia, leukocytosis or an elevated C-reactive protein (CRP) level." (PMID 33916031, 2021). "Among the 49 cases whose laboratory abnormalities were reported, the most frequently encountered changes were elevated c-reactive protein (CRP) (51%), lymphocytopenia (46.9%), elevated lactate dehydrogenase (LDH) (38.7%), elevated creatinine (26.5%), elevated D-dimer (24.4%), leukocytosis (22.4%)." (PMID 33525705, 2021). "Moreover, lower survival rate was shown from leukopenia, leukocytosis, neutrophillia, high NLR, high CRP, and prolonged PT (p = 0.015; p = 0.018, p = 0.003, p = 0.035, and p = 0.03, respectively)." (PMID 34904053, 2021). "Other previously studied parameters, such as C-reactive protein (CRP), procalcitonin or leukocytosis were not statistically significant." (PMID 34922448, 2021). "The postnatal age of LOS onset, the number of LOS episodes, the type of microorganism found in the blood culture, a CRP value > 45 mg/L, leukocytosis or leukopenia, and use of cardiotonics were not different in the BPD versus no BPD group." (PMID 33629121, 2021). "Since chronic inflammation usually leads to leukocytosis, anemia, thrombocytosis, and elevated ESR, CRP, C3, and C4, laboratory tests including WBC, Hb, PLT, ESR, CRP, C3, and C4 are routinely performed at our clinics to provide another objective parameters for JIA evaluation." (PMID 33926518, 2021). "The follow-up laboratory data on postoperative day 3 revealed that the IA group had more patients with leukocytosis than the EA group (white blood cell [WBC] ≥ 10000/mm3: 49% vs. 28.6%, p = 0.004) and a higher C-reactive protein (CRP) level (88.1 vs. 63.3 mg/L, p < 0.001)." (PMID 33397412, 2021). "All 98 cases exhibited elevated C-reactive protein, and 92.9% had thrombocytopenia and neutrophilia, most without leukocytosis, likely due to compensatory reduction of lymphocytes." (PMID 32308194, 2020). "General laboratory tests may be nonspecific in patients with bacterial pericarditis but anemia and leukocytosis with a left shift are commonly present in addition to increased ESR and CRP." (PMID 32733623, 2020).
leukocytosis (continued). "The analysis of these data showed that pain and fistula formation were the most reported clinical findings and that no patient had leukocytosis (mean C-reactive protein level [CRP] of 31.2 mg/dL and mean sedimentation rate [SR] of 34.8 mm/h)." (PMID 32282732, 2020). "Our patient had mild leukocytosis with neutrophilia with elevated ESR and CRP." (PMID 32905408, 2020). "AOSD can lead to leukocytosis, increased neutrophil percentage, thrombocytopenia, inflammatory anemia, increased erythrocyte sedimentation rate (ESR) and C-reactive protein (CRP) level, mild to moderate abnormalities in blood coagulation, and abnormal liver function." (PMID 33246419, 2020). "Additional tests revealed mild leukocytosis (11.1 × 103/μl) with left shift (81.2% neutrophils) and negative C-reactive protein (CRP; < 0.5 mg/L)." (PMID 32921316, 2020). "The most frequent symptoms are fever and headache and the most frequent analytical alterations are thrombocytopenia and neutrophilia without leukocytosis, in addition to the elevated C-reactive protein during the acute phase." (PMID 32308194, 2020). "Laboratory tests can also show inflammation such as leukocytosis, increased ESR and CRP levels." (PMID 33246419, 2020). "Laboratory findings include leukocytosis with elevated ESR and CRP." (PMID 33335818, 2020). "The analytical findings in our series were similar to those previously reported, i.e., lymphopenia without significant leukocytosis, thrombocytopenia, and high CRP and PCT." (PMID 33243303, 2020). "Blood biological tests revealed CRP elevation (165 mg/L) without leukocytosis (4,100/mm3) or thrombocytopenia (198 G/L)." (PMID 31769401, 2020). "Laboratory findings, including anemia, leukocytosis, erythrocyte sedimentation, and C-reactive protein, are not specific." (PMID 32504253, 2020). "Typical laboratory findings include leukocytosis with neutrophilia, hyperferritinemia, high transaminases, and elevated acute-phase reactants, such as erythrocyte sedimentation rate (ESR) and C-reactive protein (CRP)." (PMID 33195296, 2020). "Interestingly, leukocytosis, LDH, procalcitonin and C-reactive protein (CRP) levels were considerable in patients with ocular symptoms." (PMID 32851877, 2020). "Another interesting finding is that CRP was not correlated to the leukocytosis, but to the increase of CK and AST, which both are intracellular enzymes used as markers of cell damage." (PMID 32966338, 2020). "Among laboratory findings, leukocytosis (p = 0.004) and increased ESR (p = 0.006) observed at the 3-month assessment were significantly associated with primary inefficacy, while CRP (p = 0.10) and serum ferritin (p = 0.14) did not." (PMID 31001115, 2019). "While the absence of leukocytosis, neutrophilia, and a normal CRP would suggest a lower likelihood of acute appendicitis, this does not rule out the diagnosis." (PMID 31856705, 2019). "The temporary rise of the CRP levels in patients with 4DF application usually peaked on postoperative days 2 or 3 without accompanying leukocytosis or rise of body temperature." (PMID 31093531, 2019). "Blood tests showed the absence of leukocytosis and negative C-reactive protein (CRP), whereas procalcitonin was not available at the time of admission to the ICU." (PMID 31847889, 2019). "This patient had leukocytosis with neutrophilia, with raised ESR and positive CRP." (PMID 31472695, 2019). "In addition to amelioration of leukocytosis, SBH reduced the circulating levels of inflammatory mediators, including CRP, MCP-1, TNF-α, IL-1β and IL-6 in LPS-induced rats." (PMID 30858869, 2019). "Laboratory findings may include leukocytosis, increased erythrocyte sedimentation rate (ESR) and C-reactive protein (CRP) levels." (PMID 31480587, 2019). "Leukocytosis and elevated CRP levels are common in HAdV infection, even without superimposed bacterial infection." (PMID 31370781, 2019).
leukocytosis (continued). "But IBD patients also present nontraditional cardiovascular risks: hyperhomocysteinemia, leukocytosis, anemia, corticosteroid therapy, thrombocytosis, high levels of C-reactive protein, and increased erythrocyte sedimentation rate." (PMID 30733802, 2019). "TBE patients presented with mild leukocytosis and elevated neutrophil count as well as mildly increased CRP concentration, independent of the clinical presentation." (PMID 29678185, 2018). "First, due to the retrospective nature of the study, other markers for inflammation such as C-reactive protein, sedimentation rate and leukocytosis were not available at the time of inclusion." (PMID 30176828, 2018). "Significantly increased leukocytosis, peripheral blood neutrophilia, and C-reactive protein, but not erythrocyte sedimentation rate, were observed after endotoxin in all cohorts." (PMID 29414995, 2018). "The peripheral inflammatory parameters (C-reactive protein concentration, leukocytosis) and CSF cellular parameters did not correlate with TLR3 SNPs (not shown)." (PMID 28646884, 2017). "Similarly, in other studies, leukocytosis has been reported only in 36% of children, but increased ESR was observed in 91% of children and CRP in 81% of them." (PMID 28471400, 2017). "Laboratory data on admission showed remarkable leukocytosis (leukocytes 23,500/μL, neutrophils 86.1 %, and no blast cells) and slight decrease in the serum albumin (3.5 g/dL) and C-reactive protein (CRP) levels (1.5 mg/dL)." (PMID 27737660, 2016). "Anemia, leukocytosis, thrombocytosis, elevated ESR, and CRP were present mostly in SoJIA." (PMID 26966610, 2016). "The incidences with temporarily elevated C-reactive protein levels not accompanied by leukocytosis or fever can be interpreted to be due to the metabolization of 4DryField particles." (PMID 26904672, 2016). "In two women, the C-reactive protein level exceeded 10 mg/dL (normal value <0.5 mg/dL), which was accompanied by mild leukocytosis in one of them (14.0/nL) but without elevated temperatures in both." (PMID 26904672, 2016). "Our and other cases of type II MERS showed no leukocytosis and negative CRP, suggesting no predictive values of these parameters for worse outcome." (PMID 27836006, 2016). "Although laboratory tests do not always correlate with severe injury, leukocytosis >20,000 wbc/ml, elevated CRP and pH <7.2 corroborate extent and severity of injury." (PMID 26478740, 2015). "Tests showed patients to have leukocytosis, eosinophilia, raised ESR and CRP." (PMID 25886461, 2015). "Blood examinations showed leukocytosis (WBC 23 × 103/μL, neutrophils 78.6%) and CRP 18.47 mg/dL." (PMID 25767733, 2015). "Our patientdid not have leukocytosis but both CRP and ESR wereelevated, which favours the diagnosis of OIP." (PMID 25347752, 2014). "Besides leukocytosis, an elevation of ESR, increased CRP and thrombocytosis plasma lipids are markedly altered in acute KD, with depressed plasma cholesterol, high-density lipoprotein (HDL), and apolipoprotein AI." (PMID 27643389, 2014). "The clinical presentation with no fever, absence of leukocytosis, reduced C-reactive protein, negative blood cultures, and null improvement with antibiotics supported a noninfectious process." (PMID 25309762, 2014). "Leukocytosis, ESR, C-reactive protein and fibrinogen are usually elevated during febrile episodes." (PMID 25793039, 2014). "Although our patient first revealed leukocytosis and neutrophilia at the second pyelonephritis, his CRP level was not significantly elevated (1.81mg/dl)." (PMID 25488491, 2014). "During abdominal attacks in patients with HAE, leukocytosis and high Hct without CRP elevation can be confused with an acute abdomen needing an emergency surgical procedure." (PMID 23915279, 2013).
leukocytosis (continued). "Laboratory findings often reflect a nonspecific inflammatory response, such as normochromic normocytic anemia, mild leukocytosis, elevated erythrocyte sedimentation rate (ESR) and C-reactive protein (CRP), and presence of rheumatoid factor and hypergammaglobulinemia." (PMID 23533433, 2013). "Changes in serum CRP, ESR, ALT, AST, leucocyte (leukopenia/leukocytosis), Hb (anemia), and platelet (thrombocytopenia) may be seen in patients with BEO." (PMID 24454352, 2013). "Analytic study revealed leukocytosis (12.750/μL), elevated CRP (58 mg/L), without renal graft dysfunction or other abnormalities." (PMID 24558621, 2013). "Abnormal WBC indices was the most common indicated reason for prolonging antibiotic use despite negative serial CRP values and included leukopenia (31%), neutropenia (17%), and leukocytosis (16%)." (PMID 24244325, 2013). "The concept of unfavorable treatment response was introduced and substituted for fever, leukocytosis, and lack of CRP decrease in the multivariable analysis, to avoid the multicolinearity among those three variables." (PMID 23914899, 2013). "Consideration of the likelihood of a HAE attack is important when patients present with acute abdominal pain and leukocytosis without elevation of CRP." (PMID 23915279, 2013). "Laboratory investigation discloses mild leukocytosis and elevated ESR and CRP." (PMID 17655767, 2007). "The finding that CRP levels fall significantly (p<0.001) by discharge in clinical responders, whereas WBC counts do not show a statistically significant reduction (p=0.184), underscores the limitations of relying solely on leukocytosis as a marker of resolution." (PMID 41556000, 2025). "Later on, the laboratory tests revealed a leukocytosis of 16,460/uL (3,600-11,000/uL) with neutrophilia, an elevated erythrocyte sedimentation rate of 64 mm/hour (0-20 mm/hour), and an elevated C-reactive protein of 14 mg/dL (0-0.5 mg/dL), with no other significant findings." (PMID 40556988, 2025). "Laboratory findings may show elevated inflammatory markers, including leukocytosis and elevated C-reactive protein (CRP), although these are nonspecific." (PMID 41322888, 2025). "The next day, due to the worsening of the symptoms, abdominal guarding during clinical examination, and a progressive increase in leukocytosis (19.56 × 109/L), neutrophil (14.78 × 109/L) and CRP levels (194 mg/L), surgical intervention was needed, and no additional imaging studies were performed." (PMID 40710859, 2025). "Laboratory tests revealed peripheral leukocytosis, with a white blood cell count of 18,100/mm3 (86% neutrophils) and elevated levels of inflammatory markers, including erythrocyte sedimentation rate (ESR; 81.3 mm/h) and C-reactive protein (CRP; 21.36 mg/dL) levels." (PMID 40258720, 2025). "Laboratory tests showed no leukocytosis or elevated C-reactive protein (CRP)." (PMID 41221525, 2025). "Laboratory blood tests showed leukocytosis [15.56 (3.4–9.7 × 109/L)] with neutrophil predomination [10.99 (2.06–6.49 × 109/L)] and elevated liver enzyme [AST 63 (11–34 U/L), ALT 153 (8–41 U/L), GGT 220 (9–35 U/L), ALP 185 (54–119 U/L)] and CRP levels [99.6 (<5 mg/L)]." (PMID 40710859, 2025). "However, in the absence of clinical signs, leukocytosis, or abnormal vital signs, continued observation and conservative treatment are more appropriate because the CRP levels increase during this period." (PMID 40142907, 2025). "Signs such as leukocytosis may be absent in immunocompromised patients or conflated with other conditions, whereas CRP cannot reliably distinguish between bacterial, viral, or noninfectious processes." (PMID 40806505, 2025). "Initial labs revealed leukocytosis (14.5 ×109/L) with normal eosinophil count (0.1 ×109/L), alanine aminotransferase (ALT) 210 U/L, aspartate aminotransferase (AST) 185 U/L, alkaline phosphatase (ALP) 350 U/L, C-reactive protein (CRP) 61 mg/L, and procalcitonin 2.93 ng/mL." (PMID 41041101, 2025).